MTOR (mechanistic target of rapamycin kinase)
Diseases named in the same sentence as MTOR in open-access papers (continued):
Sharing a sentence is not in itself a finding about the gene and the disease.
lymphedema (5 papers, 2017 to 2024). Excess fluid collection in tissues, causing swelling. "Between 2014 and 2022, three patients with mTOR inhibitor-associated lymphedema after transplantation had undergone lymphedema surgery such as LVA, liposuction, or lymph node transfer at single center." (PMID 38737839, 2024). "mTOR inhibitors rarely cause lymphedema by inhibiting different subtypes of VEGFs, which results in impaired lymphangiogenesis." (PMID 33080700, 2020). "Inhibitors of the mTOR pathway must be prescribed with caution, especially to patients at high risk of developing lymphedemas." (PMID 33080700, 2020). "However, mTOR inhibitors have been associated with various adverse effects including lymphedema." (PMID 38737839, 2024). "Although rare in incidence, previously known treatments for mTOR inhibitor-induced lymphedema were limited to discontinuation of related drugs and complex disruptive therapy with variable results." (PMID 38737839, 2024). "In conclusion, this series presents the first physiologic approach to mTOR inhibitor-induced lymphedema." (PMID 38737839, 2024). "Other reasons for mTOR inhibition were refractory epilepsy (23.5%) and one rare case of congenital focal lymphedema of the leg (5.9%)." (PMID 31053163, 2019). "This series presents the first physiologic approach to mTOR inhibitor-induced lymphedema." (PMID 38737839, 2024). "Thus, three lymphedema patients (five lower limbs) induced secondarily by mTOR inhibitor underwent physiologic surgical approach to improve the symptoms." (PMID 38737839, 2024). "In this article, three patients who developed lymphedema in their lower limbs after using mTOR inhibitors, including two bilateral and one unilateral case, were treated with physiologic surgery methods such as lymphovenous anastomosis (LVA) and lymph node transfer." (PMID 38737839, 2024). "This is the first report using physiologic surgery against mTOR inhibitor-induced lymphedema." (PMID 38737839, 2024). "Therefore, although effective imaging modalities may enhance the success rate of physiologic surgery, their impact on surgical outcomes in mTOR inhibitor-induced lymphedema remains uncertain." (PMID 38737839, 2024). "Although further studies are warranted to see the effects of physiologic surgery against mTOR-induced lymphedema, due to the scarcity of mTOR inhibitor-induced lymphedema, this report of three patients (five limbs and one genital lymphedema) may shed early light into a difficult problem." (PMID 38737839, 2024). "Another factor that needs further investigation is why some patients develop lymphedema while the majority of the patients with prolonged use of mTOR inhibitor do not." (PMID 38737839, 2024). "Bilateral mTOR-related oedemas are usually controlled with low doses of furosemide accompanied by reducing the immunosuppressant, but not in lymphedema." (PMID 33080700, 2020). "First, the lymphatic vessels of mTOR inhibitor-induced lymphedema patients may have degenerated and nonfunctioning lymphatic vessels based on the duration of drug use." (PMID 38737839, 2024).
malignant mesothelioma (5 papers, 2015 to 2025). A malignant neoplasm of the pleura or peritoneum, arising from mesothelial cells. "This is consistent with previous studies evaluating compounds targeting the PI3K/mTOR pathway in malignant mesothelioma." (PMID 33660194, 2021). "This justifies the need to target the PI3K/mTOR pathway in patients diagnosed with malignant mesothelioma." (PMID 33660194, 2021). "As mTOR activity is aberrantly upregulated in the case of NF2 inactivation, suppressing mTOR activity by LY3023414 might be considered beneficial for treatment of malignant mesothelioma." (PMID 33660194, 2021). "In malignant mesothelioma, NF2/merlin inactivation is observed in approximately 40% of cases, indicating its critical role in cancer development and progression, which is associated with the activation of the Hippo and mTOR signaling pathways involved in cancer progression." (PMID 39712860, 2025). "Together, these findings indicate that AKT-mediated inhibition of mTOR by rapamycin or LY294002 attenuates apoptosis induced by pemetrexed and simvastatin combination in malignant mesothelioma and NSCLC cells." (PMID 26334320, 2015). "In NSCLC and malignant mesothelioma cells, the activation of PTEN transcription by Notch1 upregulation has been observed to lead the prosurvival phosphatidylinositol 3-kinase (PI3K)/Akt/mammalian target of rapamycin (mTOR) signaling pathway." (PMID 27847554, 2016).
myotonic dystrophy type 1 (5 papers, 2013 to 2025). Steinert disease, also known as myotonic dystrophy type 1, is a muscle disease characterized by myotonia and by multiorgan damage that combines various degrees of muscle weakness, arrhythmia and/or cardiac conduction disorders, cataract, endocrine damage, sleep disorders and baldness. "In myotonic dystrophy type 1 (DM1), which affects adults causing atrophy and myotonia, autophagy levels are enhanced and counteracting autophagy by mTOR stimulation improves satellite cells proliferation." (PMID 33363161, 2020). "Moreover, induction of autophagy and inhibition of the mTOR pathway have been found in human myoblasts of myotonic dystrophy type 1 (DM1), a noncoding repeat expansion RNA toxicity diseases due to gain-of-function effect of the RNA of the DMPK gene." (PMID 23626835, 2013). "Analyses correlating the changes in the Akt/mTOR/p70S6K signaling pathway with the pathological alterations in skeletal muscle of myotonic dystrophy type 1 (DM1) patients have revealed extensive activation of this pathway, which consequently leads to pathological hypertrophy of muscle fibers." (PMID 41195013, 2025).
nasal polyps (5 papers, 2009 to 2025). "Here we demonstrate for the first time that the mTOR signaling pathway is associated with Foxp3+ Tregs insufficiency in nasal polyps." (PMID 19250527, 2009). "Alternatively, we used rapamycin, a specific inhibitor of mTOR, in this study, and provide evidence that blocking the mTOR signal is associated with Foxp3 expression and Foxp3+ Treg expansion in cultured nasal polyps." (PMID 19250527, 2009). "Deficient apoptosis and autophagy through MAPK/JNK and PI3K/mTOR pathways may have a role in the pathogenesis of nasal polyposis." (PMID 32001208, 2021). "Our results provide the first evidence that the activation of the mTOR signaling pathway may play an important role in Foxp3+ Tregs insufficiency in nasal polyps and that blocking the mTOR signal with rapamycin is associated with Foxp3+ Treg expansion in situ." (PMID 19250527, 2009). "Our findings are, therefore, important because they demonstrate the possible association between the mTOR signaling pathway and Foxp3+ Treg expansion in nasal polyps, which may possess clinical potential for developing strategies of treating nasal polyps." (PMID 19250527, 2009). "Therefore, the IL-10 overproduction may be caused by the inhibition of the mTOR signaling pathway, contributing to the balance of the Th1/Th2 network in cultured nasal polyps." (PMID 19250527, 2009). "Therefore, our results raised the possibility that the mTOR signaling pathway may be associated with Foxp3+ Treg insufficiency in nasal polyps." (PMID 19250527, 2009). "Rapamycin inhibits the PI3K/Akt/mTOR pathway, thereby inhibiting the differentiation of fibroblasts in nasal polyps and the production of collagen and extracellular matrix, and attenuating the occurrence of tissue remodeling." (PMID 38888464, 2024). "WB revealed significantly decreased p‐PI3K/PI3K and p‐mTOR/mTOR protein expression ratios in nasal polyps after systemic and intranasal administration of LY294002, 3‐MA, and AS605240 compared with the control." (PMID 38888464, 2024). "Meanwhile, inhibiting the PI3K/Akt/mTOR pathway and promoting autophagy can reduce the number of ILC2s and the severity of tissue remodeling in the nasal polyps of eCRSwNP mice." (PMID 38888464, 2024). "IHC further showed that, compared with the control, systemic and intranasal administration of LY294002, 3‐MA, and AS605240 significantly reduced the expression of p‐Akt and p‐mTOR in nasal polyps." (PMID 38888464, 2024). "The Akt/mTOR pathway, eosinophilic inflammation, and tissue remodeling are activated in the nasal polyps of patients with eCRSwNP or noeCRSwNP." (PMID 35747690, 2022). "This study showed that the Akt/mTOR pathway, eosinophilic inflammation, and tissue remodeling are activated in the nasal polyps of patients with eCRSwNP or noeCRSwNP." (PMID 35747690, 2022). "Immunohistochemistry was also used to evaluate autophagy, mitophagy, and Akt/mTOR pathway-related protein expression and distribution in nasal polyps and control tissues." (PMID 35747690, 2022). "We also evaluated the effects of rapamycin stimulation on the percentages of Foxp3+ Tregs and on the phosphatase and tensin homologue deleted on chromosome 10 (PTEN)/PI3K-Akt-mTOR signaling pathway in cultured nasal polyps." (PMID 19250527, 2009). "Second, it is very difficult for us, as well as other investigators, to take advantage of some reliable methods such as knockdown or mutant constructs to evaluate the importance of the mTOR signal in the development of nasal polyps." (PMID 19250527, 2009). "To address this issue, we analyzed the protein expression of phosphorylated mTOR and Foxp3 in nasal polyps." (PMID 19250527, 2009). "In the tissue culture system, we detected significantly elevated Foxp3 expression and IL-10 production, as well as an increased percentage of Foxp3+ Tregs in nasal polyps after blocking the mTOR signaling pathway with rapamycin." (PMID 19250527, 2009).
nasal polyps (continued). "To determine the possible role of mTOR signaling in Foxp3+ Treg insufficiency in nasal polyps, we investigated the percentages of Foxp3+ Tregs and cytokine profiles in a tissue culture system after treatment with rapamycin." (PMID 19250527, 2009). "One study has suggested that the Akt/mTOR pathway is activated in nasal polyp fibroblasts." (PMID 35747690, 2022). "The PI3K (p < 0.002) and mTOR (p < 0.005) immunoreactivities were increased in nasal polyposis." (PMID 32001208, 2021). "Our findings suggest that the mTOR signaling pathway may play an important role in Foxp3+ Treg insufficiency and provide some clues about the immunomodulation in nasal polyps." (PMID 19250527, 2009). "We hypothesized that a hyper-activated mTOR signaling pathway contributes to Foxp3+ Treg insufficiency in nasal polyps." (PMID 19250527, 2009). "Inhibition of the mTOR signaling pathway may be helpful for enhancement of Foxp3+ Treg expansion, as well as modulation of T cell phenotype imbalances in nasal polyps." (PMID 19250527, 2009). "However, little is known about the in situ expansion of Tregs in inflammatory tissues such as nasal polyps in response to blocking the mTOR pathway." (PMID 19250527, 2009). "In conjunction with our previous reports, we concluded that the mTOR pathway may play an essential role in the Treg insufficiency, which is characteristic of nasal polyps." (PMID 19250527, 2009). "Therefore, we hypothesize that IL-13 leads to the phosphorylation of related molecules of the mTOR/p70S6K1 pathway, promoting the proliferation and differentiation of the nasal epithelium, which leads to the generation of nasal polyps." (PMID 40438321, 2025). "Although the PI3Kγ inhibitor 3‐MA had an inhibitory effect on the PI3K/Akt/mTOR pathway, it also had an inhibitory effect on Vps34, generally reducing the level of autophagy and aggravating the degree of eosinophilic inflammation and tissue remodeling in nasal polyps." (PMID 38888464, 2024). "In order to evaluate the possible association between inhibition of mTOR signaling and Foxp3+ Treg expansion, we investigated a series of proteins, including PTEN, PI3K, pAkt, pmTOR, p4E-BP1, T-bet, GATA-3, and Foxp3 in rapamycin-stimulated nasal polyps by western blot analysis." (PMID 19250527, 2009). "In this study we aimed to investigate apoptotic (MAPK/JNK), anti-apoptotic (PI3K/mTOR) and autophagic (LC3) pathways which are related each other in the nasal polyposis tissues." (PMID 32001208, 2021). "This study found that the number of ILC2s in nasal polyps could be reduced by promoting autophagy and inhibition of the PI3K/Akt/mTOR pathway." (PMID 38888464, 2024). "In nasal polyps, the levels of PI3K/mTOR proteins are upregulated, and autophagy is downregulated." (PMID 35747690, 2022). "First, we have validated that the levels of pmTOR and p4E-BP1 were significantly decreased (by 70% and 72% for pmTOR and p4E-BP1, respectively) in rapamycin-treated nasal polyps, confirming that rapamycin functioned as a negative regulator of the mTOR pathway." (PMID 19250527, 2009).
nicotine addiction (5 papers, 2021 to 2025). "KEGG pathway analysis revealed that these dysregulated genes were primarily enriched in the neuroactive ligand‐receptor, the mTOR signaling pathway, nicotine addiction, and dopaminergic synapse." (PMID 39829117, 2025). "KEGG pathway analysis revealed that DEGs were significantly enriched in the neuroactive ligand‐receptor interaction, mTOR signaling pathway, nicotine addiction, and dopaminergic synapse." (PMID 39829117, 2025). "Many enriched pathways are close to addiction including PI3K‐Akt signalling pathway, calcium signalling pathway, mTOR signalling pathway and nicotine addiction." (PMID 39835462, 2025). "Notably enriched pathways included neuroactive ligand‐receptor interaction, mechanistic target of rapamycin (mTOR) signaling pathway, nicotine addiction, and dopaminergic synapse." (PMID 39829117, 2025). "The signaling pathways enriched by differential metabolites, such as the mToR signaling pathway, central carbon metabolism in cancer, pyrimidine metabolism, and nicotine addiction, indicate that FBXW7 may govern the incidence of CRC via these pathways." (PMID 39823500, 2025). "With respected to the KEGG pathways of genes with up-methylated m6A peaks, we found that the hyper-methylated mRNAs were enriched in biotin metabolism, morphine addiction, nicotine addiction, aldosterone synthesis and secretion, the PPAR signaling pathway, and the mTOR signaling pathway." (PMID 33653351, 2021).
Opportunistic infection (5 papers, 2014 to 2025). An infection that is caused by a pathogen that would generally not be able to cause an infection in a host with a normal immune system. "Restoration of the mTOR phosphorylation capacity along with inhibition of the TGF-βRI signaling in NK cells after severe injury might improve the immune defense against opportunistic infections." (PMID 32670280, 2020). "Reinders' group has subsequently initiated a phase II study that will include 70 renal allograft recipients to examine if MSCs with everolimus, a mammalian target of rapamycin (mTOR) inhibitor, can facilitate tacrolimus withdrawal and decrease fibrosis as well as opportunistic infection." (PMID 26933811, 2016). "The current study will test the hypothesis that MSC treatment, in combination with the mTOR inhibitor everolimus, facilitates tacrolimus withdrawal, reduces fibrosis and decreases the incidence of opportunistic infections compared to standard tacrolimus dose." (PMID 25491391, 2014). "Still, mTOR-based regimens might remain a strategic option to reduce opportunistic infections." (PMID 40872883, 2025).
penile cancer (5 papers, 2018 to 2025). A primary or metastatic malignant neoplasm that affects the penis. "These shared findings between VSCC and penile cancer might open possibilities for the enrollment in trials exploring the role of NOTCH-1 mutations as predictors of response to PI3K/mTOR inhibitors." (PMID 34209172, 2021). "This preliminary study shows the implication of mTOR/AKT signaling pathway-related proteins in clinical outcomes among patients with advanced penile cancer." (PMID 41008800, 2025). "The PI3K/mTOR/AKT pathway might represent an intriguing option for treatment of penile cancer (PeCa)." (PMID 34066040, 2021). "Similarly, the PI3K/mTOR/AKT pathway might represent an alternative option for the treatment of penile cancer." (PMID 41008800, 2025). "Analysis of the PI3K-AKT-mTOR pathway in different disease states of penile cancer revealed more common expression of nuclear p-AKT and cytoplasmic p-mTOR in PeIN than primary PSCC (p<0.0001 and p = 0.0006, respectively)." (PMID 29902261, 2018).
Peritoneal Fibrosis (5 papers, 2019 to 2025). Disorder characterized by a wide range of structural changes in PERITONEUM, resulting from fibrogenic or inflammatory processes. "In conclusion, LY294002 and rapamycin promoted expression of autophagy-related proteins LC3-II/I, p62, and beclin-1 through regulating PI3K/AKT/mTOR signalling pathway to resist the process of peritoneal fibrosis in vitro and in vivo." (PMID 35309056, 2022). "In summary, the mTORC1-specific blocker did not induce p-Akt up-regulation through negative feedback, and RAPA and BEZ235 both significantly down-regulated the mTOR pathway to inhibit the development and progression of peritoneal fibrosis." (PMID 30982374, 2019). "In future works, we will keep exploring the related mechanisms of mTOR blockers in treating peritoneal fibrosis." (PMID 30982374, 2019). "The p-Akt, p-mTOR, p-p70S6K expression levels were significantly up-regulated in the 3 W group compared to the NS group, confirming that the mTOR pathway was significantly activated during peritoneal fibrosis." (PMID 30982374, 2019). "In this study, we observed the regulation of the mTOR pathway in rats with peritoneal fibrosis by RAPA and BEZ235 to compare the anti-peritoneal fibrotic functions of these 2 different types of mTOR pathway blockers." (PMID 30982374, 2019).
placental insufficiency (5 papers, 2016 to 2025). Failure of the placenta to deliver an adequate supply of nutrients and oxygen to the fetus. "The combined effects of complement dysregulation, inflammation, and mTOR inhibition likely exacerbate placental insufficiency, reducing fetal nutrient delivery and growth." (PMID 41227380, 2025). "Reduced placental mTOR activity may impair mitochondrial respiration and contribute to placental insufficiency in IUGR pregnancies." (PMID 30670706, 2019). "Our findings are consistent with the possibility that reduced placental mTOR activity in IUGR18–20 may impair mitochondrial respiration and contribute to placental insufficiency in this pregnancy complication." (PMID 30670706, 2019).
pulmonary tuberculosis (5 papers, 2019 to 2023). A bacterial infection that affects the lungs and is caused by Mycobacterium tuberculosis. "This study investigated the association between PI3K/AKT/mTOR pathway autophagy-related gene polymorphisms and pulmonary tuberculosis (PTB) susceptibility." (PMID 37493735, 2023). "In pulmonary tuberculosis, hsa_circ_0005836 is related to the regulation of the mTOR signaling pathway." (PMID 37651321, 2023). "Other studies have shown that PI3K/AKT/mTOR signaling pathways are suppressed in patients with active pulmonary TB." (PMID 35419455, 2022). "MTOR had 9396 genetic variations in dbSNP, and two SNPs, rs6701524 and rs10492975, are related to pulmonary tuberculosis." (PMID 30380109, 2019). "Similarly, in lung TB patients receiving adjunctive mTOR inhibition therapy together with appropriate antimicrobial treatment had possible, transient improvement in lung function." (PMID 36103894, 2022).
respiratory distress syndrome (5 papers, 2013 to 2024). "It is demonstrated that aberrant activation of the Akt-mTOR pathway in the lung epithelium contributes to the pathophysiology of respiratory distress syndrome." (PMID 38541642, 2024).